IL26 (interleukin 26)
Diseases named in the same sentence as IL26 in open-access papers (continued):
Sharing a sentence is not in itself a finding about the gene and the disease.
Sepsis (5 papers, 2019 to 2024). Sepsis is defined as life-threatening organ dysfunction caused by a dysregulated host response to infection. "The current study extends these findings, not only by showing elevation of serum IL-26 in a well-defined cohort of septic patients, but also by providing information on correlations between serum IL-26 levels and sepsis-associated disease severity." (PMID 31464651, 2019). "We opted for a ready-made reagent kit for cytokine analysis, which led to the omission of several well-recognized cytokines associated with sepsis progression, such as CXCL-1, IL-18, IL-26, and IL-27." (PMID 38707899, 2024). "Previous studies have reported disease severity-related serum IL-26 elevations in cases of systemic lupus erythematosus, BD, and sepsis." (PMID 35463017, 2022). "To further investigate the role of IL-26 in the pathogenesis of sepsis, we established a clinically relevant murine model of sepsis induced by CLP." (PMID 31464651, 2019). "This study firstly assessed the production of serum IL-26 in patients with sepsis, resulting in three main findings." (PMID 31464651, 2019). "In this study, we aimed to determine the extent of systemic IL-26 expression in patients with sepsis and to investigate the relationship of IL-26 to disease severity and survival in human sepsis." (PMID 31464651, 2019). "In experimental sepsis, we demonstrated a previously unrecognized role of IL-26 in increasing lethality despite promoting antibacterial host responses." (PMID 31464651, 2019). "This study firstly showed that the serum IL-26 level was significantly elevated in human sepsis on day of ICU admission, which correlated with disease severity and 28-day mortality." (PMID 31464651, 2019). "Here we demonstrated that IL-26 was an important sepsis-related proinflammatory cytokine, which contributed to inflammatory response, organ injury, and mortality in murine sepsis." (PMID 31464651, 2019). "On the day of ICU admission, the patients with sepsis showed a significant increase in serum IL-26 levels compared with ICU patient controls and healthy volunteers, and the serum IL-26 levels were related to the severity of sepsis." (PMID 31464651, 2019). "Higher serum IL-26 levels were related to higher SOFA scores in the patients with sepsis on day of ICU admission." (PMID 31464651, 2019). "Overall, our data demonstrated that IL-26 contributed to inflammatory response, organ injury, and mortality in murine sepsis despite enhancing the host’s ability to fight pathogens." (PMID 31464651, 2019). "Second, the serum IL-26 levels were related to the severity of sepsis, including parameters such as CRP, PCT, the length of ICU stay, and SOFA score." (PMID 31464651, 2019). "Additionally, IL-26 administration aggravates oxazolone-induced AD in mice via the promotion of the Th2 and Th17 response and increases mortality in mouse models of sepsis, accompanied by increased infiltration of neutrophils into the peritoneal cavity." (PMID 35463017, 2022). "In an earlier study, circulating IL-26 levels were found to be significantly elevated in sepsis patients and to be correlated with severity and survival, and peritoneal inflammatory responses were found to be increased in septic mice treated with recombinant human IL-26." (PMID 33628366, 2021). "In addition, administration of recombinant human IL-26 significantly increased the pathology scores for the lungs, livers, and kidneys after sepsis at 24 h after CLP." (PMID 31464651, 2019). "Given that mice do not express IL-26 and mice express both receptor chains that are necessary to form IL-26 receptor complexes, we therefore examine the effects of recombinant human IL-26 on the pathogenesis of sepsis in a CLP-induced polymicrobial sepsis model." (PMID 31464651, 2019). "Further investigations are warranted to investigate whether IL-26 treatment or blockade in sepsis has the potential to influence the outcome of the disease in humans." (PMID 31464651, 2019).
Sepsis (continued). "Taking into consideration the beneficial effects of IL-26 on bacterial clearance, we can speculate that IL-26 elevation during sepsis is an immunoregulatory mechanism that is initiated by the host to combat bacterial infection." (PMID 31464651, 2019). "Third, a high serum IL-26 level on the day of ICU admission was associated with 28-day mortality in septic patients, and IL-26 was found to be an independent predictor of 28-day mortality in the patients with sepsis." (PMID 31464651, 2019). "Fifth, the kinetics of IL-26 secretion, the cellular source of IL-26, and the factors regulating IL-26 production in human sepsis remain unknown." (PMID 31464651, 2019). "Furthermore, administration of recombinant human IL-26 increased lethality in CLP-induced polymicrobial sepsis." (PMID 31464651, 2019). "Furthermore, our data demonstrated a previously unrecognized role of IL-26 in increasing lethality during experimental sepsis despite promoting antibacterial host responses." (PMID 31464651, 2019). "In addition, we examined the potential role of IL-26 in host immune responses to murine sepsis by administration of recombinant human IL-26 protein." (PMID 31464651, 2019). "Therefore, we should point that the net effect of endogenous IL-26 on the outcome of human sepsis is determined by the balance between its local effects (facilitating the clearance of microorganisms) and its systemic effects (exaggerating inflammation)." (PMID 31464651, 2019). "The lowest dose of recombinant human IL-26 (0.5 μg) decreased sepsis survival from 80% (in PBS-treated septic mice) to 40%, and the highest dose of recombinant IL-26 (1.0 μg) decreased survival to 20%." (PMID 31464651, 2019). "Previous studies had identified several biomarkers such as oncostatin M (OSM), apoptosis inhibitor of the macrophage (AIM/CD5L), interleukin-26 (IL-26), interleukin-17D (IL-17D), interleukin-37 (IL-37), and growth differentiation factor-15 (GDF-15) as potential predictors of sepsis prognosis." (PMID 38318247, 2024). "In addition, the effects of recombinant human IL-26 on host inflammatory response in cecal ligation and puncture (CLP)-induced polymicrobial sepsis were determined." (PMID 31464651, 2019). "Since the murine genome does not appear to contain a paralog of the IL-26 gene, we could not use IL-26-knockout mice to examine the contribution of IL-26 to host immune response during sepsis." (PMID 31464651, 2019). "Serum IL-26 concentrations on ICU admission were significantly increased in septic shock patients compared to septic patients without shock, and non-surviving patients with sepsis showed significantly higher IL-26 levels compared to survivors with sepsis." (PMID 31464651, 2019).
ulcerative colitis (5 papers, 2010 to 2025). An inflammatory bowel disease involving the mucosal surface of the large intestine and rectum. "Genome-wide association studies have identified interleukin-26 (IL-26) as a risk locus for ulcerative colitis (UC), indicating a potential role of this cytokine in intestinal homeostasis." (PMID 41125850, 2025). "More recently, a meta-analysis identified the il-26 gene-containing region as an ulcerative colitis risk locus." (PMID 23055831, 2012). "The interleukin (IL)-20 subfamily of cytokines consists of IL-19, IL-20, IL-22, IL-24, and IL-26, and the expression of IL-20, IL-22, and IL-24 is reported to be higher in the colon of patients with ulcerative colitis." (PMID 31311100, 2019).
Arthritis (4 papers, 2012 to 2024). Inflammation of a joint. "In support, high levels of IL-26 are detected in arthritis other than RA, including osteoarthritis crystalline arthritis (personal observation)." (PMID 23055831, 2012). "It remains to be elucidated if IL26-positive CD68+ synovial macrophages stem from circulating monocytes or from synovial tissue-resident macrophages, which both have been demonstrated in the K/BxN serum-transfer arthritis model." (PMID 38799447, 2024).
chronic obstructive pulmonary disease (4 papers, 2021 to 2025). A chronic and progressive lung disorder characterized by the loss of elasticity of the bronchial tree and the air sacs, destruction of the air sacs wall, thickening of the bronchial wall, and mucous accumulation in the bronchial tree. "Besides RA, recent studies reported that IL-26 was also found in many inflammatory lung diseases, such as asthma and chronic obstructive pulmonary disease (COPD)." (PMID 37108686, 2023). "Intriguingly, the IL-10-related cytokine IL-26 is largely expressed in human airways, and alterations in its expression are associated with decreased lung function and reductions in markers of neutrophilic inflammation in Chronic Obstructive Pulmonary Disease (COPD)." (PMID 36294822, 2022). "Moreover, there is a positive correlation between IL-26 and leukocyte and neutrophil cell concentrations in the airways of healthy subjects, with or without prior endotoxin exposure, as well as in patients with chronic obstructive pulmonary disease (COPD)." (PMID 34777376, 2021).
colitis (4 papers, 2017 to 2023). Inflammation of the colon. "Importantly, human IL-26 transgenic mice show reduced susceptibility to the acute colitis caused by dextran sodium sulfate (DSS)." (PMID 35463017, 2022). "Taken together, IL-26 seems to play multifaced roles in the different phase of colitis, and its contribution to IBD should be studied further." (PMID 35463017, 2022). "Lastly, although we explored the immunoregulatory effects of IL-26 on macrophages in vitro, further research is warranted to delineate the role of IL-26 in different phase of colitis in vivo using human IL-26 transgenic mice." (PMID 35463017, 2022). "Using these tools, the authors demonstrated that IL-26 has a protective role in the acute model of colitis in mice; however, whether IL-26 has the same protective effect under chronic inflammation conditions remains to be elucidated." (PMID 38179052, 2023). "In contrast, it has been reported that IL-26 could protect mice against acute DSS-induced colitis, which is accompanied by reduced expression of TNF, CXCL9, and CXCL10, although its precise role in chronic colitis remains unclear." (PMID 35463017, 2022).
triple-negative breast carcinoma (4 papers, 2021 to 2025). An invasive breast carcinoma which is negative for expression of estrogen receptor (ER), progesterone receptor (PR), and human epidermal growth factor receptor 2 (HER2). "IL-22 enhances migration and maintains stemness in cancer cells across multiple cancer types, and IL-26 has been linked to EGFR-TKI resistance in triple-negative breast cancer." (PMID 40452847, 2025). "Elevated IL-26 expression has been reported in triple-negative breast cancer (TNBC) compared with normal tissue and peripheral blood." (PMID 41515435, 2025). "For example, IL26 is a unique, clinically relevant, inflammatory amplifier that enhances TNBC (triple negative breast cancer) engraftment and dissemination in association with neutrophils, which has the potential as a therapeutic target." (PMID 34621670, 2021).
tuberculosis (4 papers, 2013 to 2024). A chronic, recurrent infection caused by the bacterium Mycobacterium tuberculosis. "Additionally, there is speculation that IL-26 may negatively affect antimycobacterial activity and could be considered as a candidate gene for tuberculosis susceptibility." (PMID 39003443, 2024). "In conclusion, our findings elucidated the role of IL-26 in the development of tuberculosis and its contributions to intracellular bacilli killing by macrophages through the induction of M1-polarization and ROS production." (PMID 39431054, 2024). "In contrast, the levels of circulating IL-26 in adult tuberculosis patients’ peripheral blood serum were found to be significantly lower than those in healthy individuals." (PMID 39431054, 2024). "In this study, we demonstrated that the IL-26 mRNA expression in PBMCs from active tuberculosis patients was significantly higher than that of healthy individuals." (PMID 39431054, 2024). "Based on these findings, we further confirmed that the serum levels of IL-26 in adult tuberculosis patients are lower than those in healthy individuals." (PMID 39431054, 2024). "We report here that both IL-26 gene and protein expression are significantly increased in tuberculosis and sarcoidosis." (PMID 33057074, 2020). "Since IL-26 and IL-22 can also be secreted by other tuberculosis-associated lymphocyte subsets than TH17 such as TH1 cells or by NK cells, our findings point to TH1 cells or NK cells as cellular source of IL-26 in granulomatous lesions of tuberculosis." (PMID 33057074, 2020). "Comparing lymph nodes (LN) with granulomas from tuberculosis patients to healthy controls by qPCR, we detected a significantly increased gene expression of IL26 in LN from patients suffering from tuberculosis compared to LN from healthy individuals." (PMID 33057074, 2020). "In line with the gene expression results IL-26 protein was found to be increased in LN from tuberculosis patients using immunohistochemistry." (PMID 33057074, 2020). "The detection of IL-26 in granulomatous lesions of tuberculosis is surprising since LL37, an antimicrobial peptide with great impact on tuberculosis infection, was reported to be mostly absent in these chronic lesions of tuberculosis." (PMID 33057074, 2020). "Having shown that IL-26 is highly expressed on both gene and protein levels in tuberculosis LN with granulomas—in the latent inactive disease state—packed with different immune cells, we wondered if IL-26 would play a role in cell recruitment via chemotaxis." (PMID 33057074, 2020). "IL-26 transcript levels were significantly higher in both stimulated and unstimulated cultures of tuberculosis-IRIS PBMCs (P = .008 and P = .042, respectively)." (PMID 23303806, 2013). "At 24 hours, several of the cytokines (IL-10, IL-20, and IL-26) had significantly higher transcript levels in the stimulated tuberculosis-IRIS cultures (P < .001, P = .022, and P = .004, respectively)." (PMID 23303806, 2013). "Indeed, our examination confirmed the abundant presence of IL-26 in the large granuloma of lung tissue in tuberculosis patients." (PMID 39431054, 2024). "Additionally, we also observed an abundant presence of IL-26 (red) at the periphery of large granulomas in lung tissue from tuberculosis patients." (PMID 39431054, 2024). "Nonetheless, the precise role of IL-26 in the pathogenesis of tuberculosis disease remains largely unknown." (PMID 39431054, 2024). "Interestingly, the levels of circulating IL-26 in the plasma of active tuberculosis patients were lower than those of healthy persons." (PMID 39431054, 2024). "Another possible reason is that the secreted IL-26 may be rapidly depleted or transported into infection sites during the blood circulation process in these adult tuberculosis patients as a response to combatting the disease." (PMID 39431054, 2024).
tuberculosis (continued). "Notably, a marked discrepancy exists between the up-regulated expression of IL-26 mRNA in PBMCs and the decreased circulating IL-26 levels in the plasma of tuberculosis patients." (PMID 39431054, 2024). "Additionally, exploring the dynamics of IL-26 mRNA and protein levels before and after treatments in tuberculosis patients could also yield valuable insights into the role of IL-26 in tuberculosis pathogenesis." (PMID 39431054, 2024). "Interestingly, circulating levels of IL-26 decrease after anti-tuberculosis treatment." (PMID 33057074, 2020). "In conclusion, our study revealed significant differences in IL-26 expression in PBMC and circulating IL-26 levels in the serum of tuberculosis patients compared to healthy individuals." (PMID 39431054, 2024). "Whereas analysis of fold-induction showed significant induction of IL-19, IL-20, IL-24, and IL-26 by M. tuberculosis, the differences detected between the tuberculosis-IRIS and non-IRIS groups were neither great nor statistically significant." (PMID 23303806, 2013). "In PBMCs from both tuberculosis-IRIS and non-IRIS patients, M. tuberculosis stimulation resulted in increased transcript abundance for many of the cytokines, most prominently IL-19, IL-20, IL-24, and IL-26." (PMID 23303806, 2013).
breast carcinoma (3 papers, 2020 to 2021). "Amplification of IL19, IL20, and IL24 co-occurs in ~9% of breast cancer patients, while the rate of IL26 amplification is only 2.4%." (PMID 33456560, 2021). "In addition, the expression of the five signature cytokines is negatively correlated with tumor purity in breast cancer, especially for IL-17A, IL-21, and IL-26, which indicates that these cytokines are mainly derived from immune cells such as Th17 cells rather than tumor cells." (PMID 33102239, 2020).
chronic GVHD (3 papers, 2017 to 2025). "A newly developed humanized anti-IL-26 monoclonal antibody effectively reduced T cell/neutrophil infiltration and fibroproliferation, demonstrating therapeutic potential for chronic GVHD treatment." (PMID 40943537, 2025). "The key role of IL-26 was reinforced by the demonstration that a neutralizing anti-IL-26 Ab decreased collagen deposition in pulmonary chronic GVHD in mice." (PMID 30809226, 2019). "Another recent study suggests a role of IL-26 in the pathogenesis of transplant-related obliterative bronchiolitisas IL-26+CD26+CD4+ T cells in part induces chronic GVHD of the lungs." (PMID 28819653, 2017).
hepatocellular carcinoma (3 papers, 2018 to 2025). A malignant tumor that arises from hepatocytes. "In hepatocellular carcinoma (HCC), elevated IL-26 expression in resected histological specimens may serve as a prognostic marker of unfavorable disease onset." (PMID 41516201, 2025). "Serum IL-26, a member of the IL-10 cytokine family, levels are elevated in chronic hepatitis C patients with severe liver inflammation, where IL-26 upregulates TNF-related apoptosis-inducing ligand (TRAIL) expression on NK cells and then kills HCV-infected hepatoma cells." (PMID 38668286, 2024).
lung fibrosis (3 papers, 2019 to 2025). "IL-26, a member of the interleukin family, plays a crucial role in pulmonary fibrosis associated with GVHD." (PMID 40943537, 2025). "IL-26 increases collagen synthesis by fibroblasts, promoting lung fibrosis during GVHD induced after the adoptive transfer of IL-26+ CD4+ T cells to IL-26-transgenic mice." (PMID 30809226, 2019). "We previously reported that IL-26 secreted by CD4 + T cells activates fibroblasts for collagen production via its functional receptor IL-20RA/IL-10RB, and that IL-26 has an important role in lung fibrosis of chronic graft-versus-host disease." (PMID 34021125, 2021).
melanoma (3 papers, 2017 to 2021). A malignant, usually aggressive tumor composed of atypical, neoplastic melanocytes. "IL-19 is a member of the IL-10 family, which includes IL-10, IL-19, IL-20, IL-22, melanoma differentiation-associated gene (MDA)-7 (IL-24), and AK155 (IL-26)." (PMID 31114590, 2019). "The melanoma EV-induced up-regulation of ghrelin, a 28-residue peptide hormone that accelerates the growth of MSCs and has an anti-inflammatory activity, is consistent with the down-regulation of IL-26, IL-17B, caspase-1 and CCL5." (PMID 28129640, 2017).